CD4 (CD4 molecule)
Diseases named in the same sentence as CD4 in open-access papers (continued):
Sharing a sentence is not in itself a finding about the gene and the disease.
B cell lymphopenia (24 papers, 2009 to 2026). "Immunological evaluation revealed T-cell lymphocytosis, B-cell lymphopenia, and a decreased CD4/CD8 ratio." (PMID 42318436, 2026). "Even the immunologic findings are equivocal at best, with B cell lymphopenia reported in 9/11 tested and 50% of patients having normal CD4 and CD8 T cells (12/25 measured)." (PMID 37371700, 2023). "The other is a dysregulation of lymphocytes that leads to B-cell lymphopenia and is characterized by CD4 + T cells." (PMID 37848511, 2023). "Lymphocyte subset testing typically reveals B cell lymphopenia, CD4+ T cell reduction, with an inverted CD4/CD8 ratio." (PMID 34422726, 2021). "Patients developed progressive hypogammaglobulinemia and CD4 and B cell lymphopenia with reductions in naïve CD4 and CD8 cells and reduced CD3 expression." (PMID 34456914, 2021). "Our data reveal a transient peripheral B-cell lymphopenia (count and percentage) with a nadir at D14p.i., coinciding with the plasma viremia peak and the nadir in NK and CD4+ or CD8+ T-cells." (PMID 19543531, 2009). "The combined immunological profile—persistent B cell lymphopenia, CD4 T cell/Treg depletion, and disrupted CD4/CD8 ratios—defines a distinctive immunopathological signature in moderate-to-severe cases, resembling immunological patterns in HIV/EBV co-infections." (PMID 41141591, 2025). "Further analysis demonstrated that B cell lymphopenia coincided with significant reductions in total T cells, CD4 T cells, and regulatory T cells (Tregs) during convalescence, particularly in moderate cases (LMo), where CD4/CD8 T cell ratios fell below normal thresholds." (PMID 41141591, 2025). "He recently presented with a distinct expansion of double negative T-cells and CD8+ effector T-cells with elevated activation markers (HLA-DR), alongside a severe decrease of CD4+ T-cells, CD8+ T-cells, NK-cells, and ongoing B-cell lymphopenia." (PMID 28861081, 2017). "CD4+ and CD8+ central memory subsets remained low (p = 0.0360 and p = 0.0274 respectively) and we noted B cell lymphopenia (p = 0.0041), even after excluding a patient who had recently received rituximab." (PMID 27993172, 2016). "Hyper-activated PI3Kδ induces alterations in lymphocyte populations including B-cell lymphopenia, inverse ratio of CD4+ to CD8+ T cells, impaired T-cell effector functions, increased T-cell senescence and exhaustion and low percentages of naïve CD4+ and CD8+ T cells." (PMID 40364814, 2025). "Nevertheless, immunophenotyping of lymphocytes in the patient indicated B-cell lymphopenia and abnormalities in T-cell subpopulations, with reversed ratio of CD4/CD8 T cells, decreased percentages of naive CD4, and CD8 T cells, and regulatory T and recent thymic emigrant cells." (PMID 35689244, 2022).
cardiomyopathy (24 papers, 2012 to 2024). A disease of the heart muscle or myocardium proper. "Mortality has increased in HIV-infected patients with cardiomyopathy, independently of CD4 count, sex, age, or HIV risk group." (PMID 23782480, 2013). "In summary, our results show that CD4+CD25+ Treg from patients with severe cardiomyopathy display a deficient suppressive activity, leading to uncontrolled production of pro-inflammatory cytokines (TNF-α and IFN-γ) from leukocytes." (PMID 22545173, 2012). "They observed the production of IFN-γ by CD3+ CD4+ cells in cardiomyopathy, along with the production of IL-10 by macrophages/monocytes, leading to regulation of the immune response, in indeterminate patients." (PMID 38133693, 2023). "Cardiomyopathy in HIV seropositive patients is associated with low socioeconomic status, a longer duration of HIV infection, low total lymphocyte count, low CD4 count, high HIV-1 viral load and low plasma levels of selenium." (PMID 23597299, 2013). "CD3+CD4+IL-17+ T cells from free/mild cardiomyopathy patients (3.73%) displayed increased frequency when compared to healthy individuals (0.99%)." (PMID 22545173, 2012). "Nevertheless, it was previously reported that cardiomyopathy patients exhibit a higher percentage of CD4+CD25high T cells expressing CTLA-4." (PMID 22545173, 2012). "In the present study PBMC from free/mild cardiomyopathy patients exhibited a higher expression of IL-17 in CD4+ T cells than that observed in PBMC from patients with severe/moderate cardiomyopathy and in cells from healthy individuals." (PMID 22545173, 2012). "The mean of the percentage of CD4+T cells expressing IL-17 in moderate/severe cardiomyopathy patients, Bz-treated patients and healthy individuals were 0.99±0.75, 0.90±0.58 and 0.67±0.57, respectively." (PMID 22545173, 2012). "A higher expression of CTLA-4 and Foxp3 in the CD4+CD25high T cells from free/mild cardiomyopathy patients was observed, when compared to moderate/severe cardiomyopathy patients." (PMID 22545173, 2012). "The purity of CD4+CD25+ T cells isolated from free/mild cardiomyopathy patients and severe cardiomyopathy patients were about 99%." (PMID 22545173, 2012). "Free/mild cardiomyopathy patients presented higher frequency of CD4+CD25high T cells expressing Foxp3 (P = 0.033) and CTLA-4 (P = 0.042) than moderate/severe cardiomyopathy patients." (PMID 22545173, 2012). "The impairment in suppressive activity observed in CD4+CD25+ T cells from patients suffering from severe cardiomyopathy correlates with the observation of reduced amounts of CD4+CD25+ T cells expressing CTLA-4 and Foxp3 in this group of patients." (PMID 22545173, 2012). "We next aimed to study if the reduced frequency of CD4+CD25+ T cell expressing CTLA-4 and Foxp3 that we found in severe cardiomyopathy patients correlated with deficient regulatory activities." (PMID 22545173, 2012). "When we analyzed the data obtained with the patients of all groups, we found that the percentage of CD4+T cells expressing IL-17 were expressively increased in the cardiomyopathy-free/mild group of patients (1.74±0.92) compared with all the other groups." (PMID 22545173, 2012). "In addition, the IFN-γ-induced chemokine receptors CCR5 and CXCR3 are upregulated in CD4+ T cells during established cardiomyopathy suggesting the participation of a type-1 T helper-mediated immunity (Th1) in the disease progression." (PMID 36447264, 2022). "CD4+ T cells are important for generating an immune response against the parasite, and the low frequency of these IFN-γ-producing cells with T. cruzi infections is associated with the severity of cardiomyopathy in patients." (PMID 34722343, 2021). "A low CD4+ T-cell count (mean cell count 246 ± 193 cells/mm3; normal range, 600–1000 cells/mm3) and left ventricular ejection fraction (mean range 27.9 ± 6.92%) were found in the patients with HIV-associated cardiomyopathy, as expected." (PMID 23775037, 2013).
cardiomyopathy (continued). "A CD4 count <100 appears to be an important threshold below which the risk of developing cardiomyopathy increases in African and non-African populations." (PMID 23597299, 2013). "However, CD4+CD25+ T cells from patients with mild cardiomyopathy or cardiomyopathy-free showed higher suppressive activity than those with moderate and severe cardiomyopathy." (PMID 22545173, 2012). "The mechanism leading to reduced expression of Foxp3 and CTLA-4 and consequently, deficient suppressive activity of CD4+CD25+ T cells from patients with cardiomyopathy has not been elucidated." (PMID 22545173, 2012). "Moreover, the analysis of CD4+CD25Low cells population demonstrated that free/mild cardiomyopathy patients and Bz treated patients have a higher occurrence of CTLA-4 than moderate/severe cardiomyopathy patients." (PMID 22545173, 2012). "Furthermore, the greater number of CD4+CD25− T cells of free/mild cardiomyopathy patients and Bz treated patients expressing CTLA-4 than cells from moderate/severe cardiomyopathy patients, probably contributes to the modulation of immune response in the heart." (PMID 22545173, 2012). "Finally, GSEA enrichment analysis of expression profile files showed that CD8+T cells, CD4+T cells and naive T cells had high enrichment scores in the cardiomyopathy group, while natural killer cells and regulatory T cells had high enrichment scores in the control group." (PMID 36148059, 2022). "CD4+ T cell responses improved after in vitro treatment with IL-27 and IL-7 only in subjects without signs of heart disease who have a more functional IL-27 and IL-7 axis and less exhausted immune system compared with those in patients with severe cardiomyopathy." (PMID 34061845, 2021). "Importantly, cells expressing the CD4CTL phenotype predominate among CD4+ T cells infiltrating the infected mouse cardiac tissue and are increased in the blood of Chagas patients, in which the frequency of CD4CTLs correlates with the severity of cardiomyopathy." (PMID 35670567, 2022). "To evaluate cellular responses, we first determined the overall frequency of circulating T-cell subpopulations, evaluating the frequencies of CD4+, CD8+, TCRgamma-delta+ and TCRalpha-beta+ DN T-cells in the different cardiomyopathies." (PMID 35187122, 2022). "We showed the top five most significantly enriched gene sets, among which the gene sets CD4+ T cells, CD8+ T cells, and naive T cells have high enrichment scores in the cardiomyopathy group but low scores in the control group." (PMID 36148059, 2022). "Higher frequencies of CD4+ IL-17A+ T-cells, lower levels of IL10 and IL10, and higher levels of IFNγ and TNFα are observed in individuals with more severe cardiomyopathy." (PMID 33193300, 2020). "CD4+CD25+ T cells from healthy individuals, free/mild cardiomyopathy patients and severe cardiomyopathy patients were sorted, and suppressive activity was evaluated in vitro through co-culture assay with allogeneic T cells stimulated with PHA." (PMID 22545173, 2012). "Reduced CD4+CD25+ regulatory T cell function and low levels of IL-17 also correlated with more advanced cardiomyopathy." (PMID 22545173, 2012). "The low production of polyfunctional T cells in patients with severe cardiomyopathy was not due to enhanced IL-27-induced IL-10 production, but in contrast, IL-10 was only induced in CD4+ T cells of the G0 subject group and in uninfected subjects." (PMID 34061845, 2021). "Interestingly, CD4+ T-lymphocytes dominated the inflammatory and apoptotic responses, but CD8+ T-lymphocytes played a lesser role in inducing nivolumab-mediated cardiomyopathy." (PMID 32244307, 2020). "Decreased CD25 upregulation in response to IL-7 in CD4+ T cells was observed in IFN-γ nonproducers with severe cardiomyopathy compared with IFN-γ producers and uninfected subjects." (PMID 30517089, 2018).
cardiomyopathy (continued). "High percentage of CD4+CD25+Low T cells expressing Foxp3 (P = 0.016) and CTLA-4 (P = 0.046) were also observed in free/mild cardiomyopathy patients compared with moderate severe cardiomyopathy patients." (PMID 22545173, 2012). "The high amount of CD4+CD25+ T cells expressing CTLA-4 and Foxp3 (that activate the regulatory T cell machinery) in CD4+ CD25+ T cells of free/mild cardiomyopathy and Bz treated patients may be related to high suppressor activity of these cells." (PMID 22545173, 2012). "Interestingly, the expression of CTLA-4, but not CD103, GITR and Foxp3, in CD4+CD25high T cells was decreased in moderate/severe cardiomyopathy compared with free/mild cardiomyopathy patients and health individuals." (PMID 22545173, 2012). "Likewise, our study found that change in myocardial strain was associated with PLWH's viral loads rather than CD4 counts, suggesting that viral loads may be a more meaningful indicator when evaluating HIV-associated cardiomyopathy." (PMID 37288253, 2023). "Flow cytometry analysis showed higher CD4+IL-17+ cells in PBMC cultured from patients without or with mild cardiomyopathy, in comparison to patients with moderate or severe cardiomyopathy." (PMID 22545173, 2012).
dysplasia (24 papers, 2009 to 2026). A usually neoplastic transformation of the cell, associated with altered architectural tissue patterns. "In the EMs group, 14 immune cells were mainly associated with them, among which activated B cells, natural killer T cells, neutrophils, central memory CD4 T cells, and CD8T cells were positively associated with dysplasia." (PMID 40371728, 2025). "Cell-type deconvolution using data from normal tissue samples only shows a concentration of CD4+ T cell signal signature within those with dysplasia and/or CAC and B cells within IBD samples." (PMID 38505585, 2024). "There was an association between dysplasia and CD4+-CD8+ groups (χ2=15.044; p=0.020), inflammatory infiltrate and CD4+-CD8+ groups (χ2=12.422; p=0.045), and PD-L1 expression and CD4+-CD8+ groups (χ2=8.942; p=0.047)." (PMID 35195152, 2022). "We found a significant increased infiltration of CD4+ T cells in low- and high-grade dysplasia and in EACs compared to normal esophageal mucosa." (PMID 32100077, 2020). "Both HIV and HTLV-1 infect CD4+ cells and it has been previously shown that elevated numbers of CD4+ cells are associated with HPV-related dysplasia." (PMID 27608036, 2016). "Among men, smoking, low CD4+ cell count, anal HPV-infection and related dysplasias have been positively associated." (PMID 19440442, 2009). "Interestingly, we found a significant increment in IHC scores for CD8+ and CD4+ T cells in dysplasia compared to normal gallbladder." (PMID 33326125, 2020). "A decrease in CD4/CD8 ratio in severe dysplasia cases has also been found." (PMID 32961682, 2020). "Focusing on oral dysplasia, it is difficult to analyze whether a low CD4 lymphocyte count is related to a higher risk of dysplasia or progression from LSIL to HSIL because there is no systematic screening for oropharyngeal dysplasia." (PMID 35630489, 2022). "But importantly, immune-suppressor, CD4+CD25+Foxp3+ Treg cells, which showed a gradual increase with progression of dysplasia to carcinoma in situ in 4NQO cohort, is significantly reduced after NLGP treatment." (PMID 38585261, 2024). "A detailed analysis of the literature on T-lymphocyte subpopulation studies found that in the epithelial layer of an HPV+ normal cervix, in severe dysplasia and in cancer progression, the concentrations of CD8+ TILs were significantly higher than CD4+." (PMID 37109686, 2023). "We observed increases of CD4+ T-cells, Foxp3+ T-lymphocytes, CD68+ macrophages, and IL-4+ cells during the progression of dysplasia in OLK and a parallel decrease in the expression of the inflammatory cytokine IFN-γ." (PMID 28053372, 2016). "Previous studies found no clear correlation between dysplasia and a low nadir CD4 lymphocyte count (i.e., <200 cell/μL), although most of them were affected by limited sample sizes." (PMID 35630489, 2022). "Although the etiological roles of CD163+ macrophages and intraepithelial CD4+ T cells in the development of dysplasia are unclear, CD163+ macrophages may contribute to the infiltration of intraepithelial CD4+ T cells." (PMID 26242181, 2015). "Significant increases in CD163+ macrophages and intraepithelial CD4+ T cells were observed in moderate dysplasia compared to samples without dysplasia." (PMID 26242181, 2015). "Finally, the increased presence of CD163+ MΦ and intraepithelial CD4+ Th1 cells observed in the presence of moderate OED, compared to samples without dysplasia, could be associated with an increased immunogenicity of dysplastic keratinocytes." (PMID 40432828, 2025).
intestinal infection (24 papers, 2009 to 2026). "In HIV− patients, intestinal infections are the leading causes of morbidity and mortality in developing countries, but their association with CD4+ T-cell counts and hs-CRP has received only cursory attention." (PMID 31565107, 2019). "The overall risk of intestinal infection for pathogens associated with diarrhoea and other potential diarrhoeal pathogens was higher only in those with low CD4 counts." (PMID 19159487, 2009). "We investigated the association between intestinal infection,CD4 cell count and diarrhea." (PMID 24662743, 2014). "Furthermore, we demonstrate for the first time an immunoendocrine feedback loop, in which CD4+ T-cell driven weight loss via CCK reduces leptin levels which impinge on CD4+ T-cell driven effector mechanisms for gastrointestinal infection resolution." (PMID 23349631, 2013). "By favoring the development of a CD4+ type-1 phenotype of peripheral lymphocytes and cytokines, elevated testosterone levels may increase susceptibility to infections that are normally cleared via the Th-2 response, like gastrointestinal infections." (PMID 21143892, 2010). "In both models of intestinal infection, we observed defective accumulation of Irf4 heterozygous and particularly Irf4 homozygous mutant CD4+ T cells in SI and colon." (PMID 37469513, 2023). "The increase of Th1 CD4+ cells expressing IFN-γ was only observed at the early intestinal infection stage (day 6)." (PMID 31703440, 2019). "The indispensable role of CD4+ T cells in protection against intestinal infection with C. rodentium has been established in several studies." (PMID 30818341, 2019). "During T. spiralis intestinal infection, CD4+ Th2 cells are critical in host protective immune and inflammatory responses." (PMID 28069101, 2017). "Patients with multiple intestinal infections accompanied with profound and persisting diarrhoea have low CD4+ T-cell counts." (PMID 21396133, 2011). "In addition, we did not collect full maternal medical histories, which may have contained important explanatory information, such as occurrence of gastrointestinal infections, nadir CD4+ T cell counts in the peripheral blood, or signs of inflammation." (PMID 36073815, 2022). "Mice deficient in CD4+ T cells (but not CD8+ T cells) are extremely susceptible to intestinal infection with C. rodentium as well as to the systemic spread of the bacterium to extra-intestinal sites, including the mesenteric lymph nodes (MLNs), spleen and the liver." (PMID 30818341, 2019). "Previous studies demonstrated that Yoghurt enrichment with probiotics as a snack may increase CD4 levels and protect against some HIV‐related gastrointestinal infections and local inflammations." (PMID 37382253, 2023). "Interestingly, SCFAs also promote human CD4+ T cell IL-22 production, even from IBD patients, our study provides SCFAs as a new potential therapeutic target for suppressing intestine infection and inflammation, and eventually treatment of IBD patients." (PMID 32901017, 2020). "Other nontuberculous Mycobacteria intestinal infections are possible in HIV patients, such as disseminated Mycobacterium avium complex (D-MAC); however these generally occur at a CD4 cell count < 0/μL." (PMID 28819499, 2017).